UNC5D (unc-5 netrin receptor D)
Description:
Receptor for the netrin NTN4 that promotes neuronal cell survival (By similarity). Plays a role in cell-cell adhesion and cell guidance. Receptor for netrin involved in cell migration. Plays a role in axon guidance by mediating axon repulsion of neuronal growth cones in the developing nervous system upon ligand binding (By similarity). May play a role in apoptosis in response to DNA damage. It also acts as a dependence receptor required for apoptosis induction when not associated with netrin ligand. Mediates cell-cell adhesion via its interaction with FLRT3 on an adjacent cell (By similarity).
Synonyms: KIAA1777; UNC5H4; PRO34692
Tractability: Antibody: UniProt places it where antibodies can reach, with high confidence; its Gene Ontology location is reachable by antibodies, with high confidence; UniProt predicts a signal peptide or a membrane-spanning region. PROTAC: its protein half-life has been measured.
Gene: Protein-coding gene on chromosome 8 (35,235,475 to 35,796,550, forward strand). Ensembl gene ENSG00000156687.
Subcellular location: Cell membrane
Pathways (Reactome):
Developmental Biology: Netrin mediated repulsion signals
Gene Ontology:
Molecular function: netrin receptor activity
Biological process: cell-cell adhesion; axon guidance; netrin-activated signaling pathway; signal transduction
Cellular component: plasma membrane; membrane
Genetic constraint (gnomAD): Loss-of-function variants: 38 observed, 105.36 expected, observed/expected ratio (o/e) 0.36, 90% interval 0.28 to 0.47. The upper end of that interval is the gene's LOEUF score, 0.47, which puts it in group 2 of 6, group 1 being the genes least tolerant of losing a copy. Missense variants: 980 observed, 1,220.1 expected, observed/expected ratio (o/e) 0.8, 90% interval 0.76 to 0.85. Synonymous variants: 452 observed, 459.99 expected, observed/expected ratio (o/e) 0.98, 90% interval 0.91 to 1.06.
Homologues: Orthologues: chimpanzee UNC5D (99% identical), macaque UNC5D (99% identical), dog UNC5D (98% identical), rabbit UNC5D (98% identical), pig UNC5D (97% identical), mouse Unc5d (96% identical), rat Unc5d (96% identical), guinea pig UNC5D (95% identical), tropical clawed frog unc5d (79% identical), zebrafish unc5db (66% identical), zebrafish unc5da (65% identical), Drosophila melanogaster unc-5 (28% identical), and 1 more. Paralogues in human: UNC5B (51% identical), UNC5C (49% identical), UNC5A (39% identical), UNC5CL (13% identical).